WASH5P (WASP family homolog 5, pseudogene)
Gene: Transcribed processed pseudogene on chromosome 19 (66,320 to 66,492, reverse strand). Ensembl gene ENSG00000282458.
Diseases named in the same sentence as WASH5P in open-access papers:
WASH5P is named in the same sentence as 5 diseases in open-access papers, as found by Europe PMC text mining. Sharing a sentence is not in itself a finding about the gene and the disease. The quoted sentences say what the papers report.
breast carcinoma (1 paper, 2019). "Finally, WASH5P is a pseudogene that is differentially methylated in early-stage breast cancer." (PMID 31548358, 2019).
colon adenocarcinoma (1 paper, 2022). "Summarized data from TCGA-COAD (The Cancer Genome Atlas-Colon Adenocarcinoma) and GTEx (the Genotype-Tissue Expression) validated that the expression level of WASH5P was significantly lower in cancer tissues than in normal tissues (P<0.001)." (PMID 35898869, 2022).
cancer (2 papers, 2019 to 2022). A tumor composed of atypical neoplastic, often pleomorphic cells that invade other tissues. "MDM4, MRTFA, and WASH5P were each highly up-regulated in embryos of poor morphology and are each in some way implicated in cancer." (PMID 31548358, 2019).
tumor (2 papers, 2017 to 2022). "WASH5P overexpression could inhibit tumor growth in the mouse model when compared with the control group." (PMID 35898869, 2022). "The transwell assay revealed that lncRNA WASH5P upregulation could significantly inhibit tumor migration and invasion when compared with the control group." (PMID 35898869, 2022). "To further identify the involvement of WASH5P in vivo, we established the xenograft tumor model." (PMID 35898869, 2022). "The overexpression of lncRNA WASH5P in HCT116 and SW480 could dramatically inhibit tumor cell viability." (PMID 35898869, 2022). "Furthermore, we analyzed the expression of vimentin, E-cadherin, p-AKT, and AKT in the tumor mass and found that vimentin and p-AKT were decreased in the WASH5P-overexpressed group compared to normal control." (PMID 35898869, 2022).
WASH5P also shares sentences with these, for which no sentence is quoted: colorectal cancer (1 paper).